RAD51 (RAD51 recombinase)
Diseases named in the same sentence as RAD51 in open-access papers (continued):
Sharing a sentence is not in itself a finding about the gene and the disease.
melanoma (continued). "Therefore, we analyzed gene expression of the important HRR genes BRCA1, BRCA2, RAD51, and EXO1 after MAPKi treatment in MAPKi S, R, and RR A375 melanoma cells." (PMID 37674529, 2023). "Furthermore, 4 melanoma pathway genes (CDKN1A, CDKN2A, CXCR4 and RAD51) were also expressed differently in normal tissues compared with melanoma." (PMID 38070141, 2023). "Among the different genes of the HRR pathway, especially the expression level of the RAD51 gene has a negative influence on the survival of melanoma patients." (PMID 32719412, 2020). "Next, we asked whether MAPKi resistant melanoma cells respond to the combined inhibition of MAPK pathway and Rad51." (PMID 32719412, 2020). "Within this work, we investigated the potential of Rad51 as therapeutic target in metastatic melanomas with or without acquired resistance to inhibitors of the MAPK pathway (MAPKi) as single agents or in combined treatments." (PMID 32719412, 2020). "Since increased HRR genes expression and in particular the expression of RAD51 mediate an upregulation of HRR capacity in cancer cells, we have analyzed whether Rad51 protects melanoma cells from DNA damage by increasing HRR capacity." (PMID 32719412, 2020). "Moreover, MAPKi-resistant melanoma cells consistently underwent a prominent increase of endogenous NOTCH1 levels and a cell-type dependent increase of the other two miR-204-5p targets RAD51 and FOXM1." (PMID 30254376, 2019). "RAD51 protein levels in A375 melanoma cells had already reduced by 50% after 24 h of 3 μM cisplatin treatment, with no equivalent reduction seen in non-melanoma cells." (PMID 29254481, 2017). "Here we identify and characterise a novel DNA damage response mechanism in melanoma, involving inactivation of the key HRR protein RAD51 and increased translesion synthesis DNA polymerase activity, that allows melanoma cells to continue to grow in the presence of cisplatin." (PMID 29254481, 2017). "The non-melanoma lines showed no reduction in RAD51 levels, even at the highest cisplatin concentration, showing that the difference in the RAD51 response of melanoma and non-melanoma lines to cisplatin is not simply a dose effect." (PMID 29254481, 2017). "The RAD51 response of the melanoma lines was seen across a range of cisplatin concentrations up to 3 μM, which is cytotoxic for all melanoma and non-melanoma cell lines studied." (PMID 29254481, 2017). "RAD51 mRNA levels also fell progressively with cisplatin treatment in the other two melanoma cell lines examined, C32 and G361, albeit not to the same extent as seen in A375." (PMID 29254481, 2017). "The response of A375 melanoma cells was very different with no significant (P = 0.44) increase in RAD51 foci after cisplatin." (PMID 29254481, 2017). "Although there were some discrepancies between RAD51 protein and mRNA levels, we conclude that the cisplatin-induced reduction in RAD51 levels in melanoma cells is due to reduced RAD51 mRNA levels rather than increased proteolysis." (PMID 29254481, 2017). "The situation was very different in the non-melanoma lines at the same time point, where none showed any RAD51 reduction and, for MRC5v1 and PEO4, increased RAD51 protein expression after 72 h of 1 and 3 μM cisplatin treatment was evident." (PMID 29254481, 2017). "Therefore, we have analyzed the formation of nuclear Rad51 foci and pH2AX foci after genotoxic stress via cisplatin treatment in melanoma cells with or without prior Rad51 inhibition." (PMID 32719412, 2020). "Interestingly, we found that melanoma cells, which developed resistance towards MAPKi are still sensitive to Rad51 inhibition allowing treatment with Rad51is regardless of the resistance status." (PMID 32719412, 2020).
melanoma (continued). "Next we investigated the significance and specificity of the RAD51 response of melanoma cells to cisplatin by expressing an N-terminal FLAG-tagged version of RAD51, under vector rather than endogenous RAD51 promoter control, at levels equivalent to those of the endogenous RAD51 protein." (PMID 29254481, 2017). "Notably, Rad51 inhibitors showed no apparent toxicity in mice, which warrants further research into clinical application of Rad51 inhibitors in the treatment of cancers, including melanoma." (PMID 33800547, 2021). "To investigate whether this unexpected RAD51 response to cisplatin was peculiar to A375 cells, or was instead a more general feature of melanoma, we assembled a panel of metastatic (A375, G361, HBL) and primary (C32 and WM115) human melanoma cell lines for further study." (PMID 29254481, 2017). "Protein expression status of LIG4, RAD51, PARP1, Ku70 was determined by Western blot analysis in normal melanocytes and melanoma cell lines (DMBC11, DMBC12)." (PMID 27705909, 2016).
colon carcinoma (27 papers, 2012 to 2025). "Finally, we explored the association of AKT activity with TopBP1 and RAD51 expression in colon cancer cells." (PMID 28573382, 2017). "This was illustrated by siRNA-mediated knockdown of the HR-mediator RAD51 in colon cancer cells, which potentiated the cytotoxicity of olaparib monotreatment and in combination with SN38." (PMID 39456536, 2024). "In colon cancer cell models, knockdown of E2F1 was correlated with loss of RAD51 expression and RAD51-dependent DSB repair; furthermore, E2F1 and BRIT1 (MCPH1) were shown to form a complex that activates the transcription of BRCA1, CHK1, p73 and CASP7." (PMID 34208195, 2021). "Single knockdown of Akt1 and Akt2 leads to a decrease in Rad51 foci formation and significantly reduces Rad51 protein level in colon cancer cells." (PMID 32711558, 2020). "In agreement with this study, we demonstrate here significantly reduced Rad51 foci formation when AKT1 as well as AKT2 isoforms were downregulated alone or in combination with HCT116 colon cancer cells." (PMID 31847370, 2019). "In our previous studies, we showed that CHK1 inhibition with prexasertib or PF-477736 downregulated expression of RAD51 in colon cancer cells." (PMID 31492187, 2019). "In the present study, we demonstrated that HGF moderately activated Chk1 phosphorylation in colon cancer cells by upregulating TopBP1 and RAD51, and promoting TopBP1–ATR complex formation." (PMID 28573382, 2017). "We determined the RAD51 foci formation in the PARPi-sensitive and -resistant colon cancer cells following treatment with PARPi." (PMID 27197561, 2016). "We sought to detect a depletion of RAD51 in NPC cells treated with Abexinostat as previously reported for the human colonic carcinoma cells HCT116 and multiple myeloma cell lines treated by HDAC inhibitors." (PMID 24618637, 2014). "The effect of JNJ-585 on RAD51 are in line with results from others demonstrating that HDACi downregulate RAD51 in colon cancer and Chinese hamster ovary cells and inhibit irradiation-mediated RAD51 foci formation." (PMID 24833108, 2014). "Moreover, the use of olaparib and SN-38, an active metabolite of irinotecan, showed a synergistic effect in colon cancer cells and an enhancement of the RAD51-mediated HR signaling pathway." (PMID 36142413, 2022). "Regulation of RAD51 by MAPKi activity is also observed in KRAS mutant colon cancer cells." (PMID 32719412, 2020). "Evidence is yielded by this study that RAD51 and XRCC2 gene polymorphisms may be risk factors for colon cancer progress." (PMID 32458654, 2020). "We hypothesized that BARD1β expression in the PARPi-sensitive colon cancer cells impacts HR proficiency, which can be measured by the formation of RAD51 foci." (PMID 27197561, 2016). "After treatment with PARPi, PARPi-resistant cells (SW480) displayed increased RAD51 foci formation compared to PARPi-sensitive colon cancer cells (Caco-2) which displayed a significantly weaker HR DNA repair response characterized by lower RAD51 foci formation." (PMID 27197561, 2016). "Furthermore, E2F1 depletion may have suppressed the HR pathway by interfering with RAD51-mediated DNA recombination and the accumulation of ssDNA gaps, impairing DNA damage repair mechanisms in colon cancer cells." (PMID 31534120, 2019). "Impact of RAD51 inhibitor and/or a DNA-damaging agent was assessed on viability and apoptosis in EAC, breast and colon cancer cell lines in vitro and in a subcutaneous tumor model of EAC." (PMID 36428789, 2022). "We investigated RAD51 expression in normal and cancer samples from clinical datasets of esophageal adenocarcinoma (EAC: GSE13898) and colon cancer (GSE33113) patients." (PMID 36428789, 2022). "In HCT116 colon cancer cells we had previously found within 1h of GZ17-6.02 exposure that the expression of XPA and XPD had declined and the levels of RAD51 and RAD52 were enhanced." (PMID 36408163, 2022).
colon carcinoma (continued). "Expression of RAD51 was significantly elevated in EAC and colon cancer samples relative to corresponding normal controls (p < 0.04)." (PMID 36428789, 2022). "The level of RAD51 transcript significantly decreased in HEK293 and HCT116 colon cancer cell lines when incubated with EVs transporting siRNA targeting RAD51 by electroporation." (PMID 33081785, 2020). "Decreased expression upon KRT23 knockdown was confirmed at the protein level for key molecules MRE11A, E2F1, RAD51 and BRCA1 and knockdown of KRT23 rendered colon cancer cells more sensitive to irradiation." (PMID 24039993, 2013). "Notably, the direct involvement of RAD51 (and HDR) in the repair of DNA damage induced by doxorubicin was observed in multiple myeloma and HCT-116 colon carcinoma cells." (PMID 39388244, 2024). "To determine whether colon cancer cells require E2F1 to promote HR activity to induce DNA gap processing and complete DNA replication, we examined the formation of RAD51 foci and RPA foci following the treatment of colon cancer cells with siE2F1." (PMID 31534120, 2019). "In colon cancer cells, E2F1 and specific HR proteins had accumulated at higher levels (increased by 8.9/5.7-fold for E2F1, 8.7/7.6-fold for RAD51, 11.4/10.8-fold for RAD54, and 5.9/5.1-fold for RPA in HCT116/HT29 cells, respectively) than those in normal colon cells." (PMID 31534120, 2019). "Finally, we investigated the intracellular localization of E2F1, RAD51, and replication protein A (RPA) in colon cancer cells exposed to methyl methanesulfonate (MMS), which induces DNA double-strand breaks (DSBs)." (PMID 31534120, 2019). "Furthermore, E2F1 depletion reduced the formation of RAD51 foci, but not the formation of RPA and γH2AX foci, and the accumulation of ssDNA gaps, indicating that colon cancer cells are able to undergo typical replication processes in the presence of unrepaired ssDNA gaps." (PMID 31534120, 2019).
cervical carcinoma (26 papers, 2010 to 2026). A carcinoma arising from either the exocervical squamous epithelium or the endocervical glandular epithelium. "Recently, it has been reported that inhibition of RAD51 is associated with decreased cervical cancer cell proliferation in vitro and in cervical cancer xenografts by attenuating cell-cycle transition." (PMID 37190191, 2023). "RAD51 G172T polymorphism showed association with overall survival of cervical cancer patients treated with chemoradiotherapy (CRT)." (PMID 35996502, 2022). "Another gene variant RAD51 G172T also showed association in overall survival of cervical cancer patients treated with CRT." (PMID 26571237, 2015). "In addition, it has been demonstrated that PARP1 also controls the expression of RAD51, a protein already associated with chemo-radioresistance in cervical cancer." (PMID 31242951, 2019). "Previous study reported that RAD51 inhibitor, RI-1, suppressed the growth of cervical cancer xenografts in vivo." (PMID 37798649, 2023). "We found that the recruitment of MDC1 in the nucleus was blocked upon LATS2 overexpression and SFN treatment, resulting in the impaired formation of Rad51 foci under ionizing radiation in cervical cancer cells." (PMID 35454780, 2022). "Association of genotypes of CYP1A1 T>C rs4646903, CYP1A1 A>G rs1048943, CYP2E1 T>A rs6413432, RAD51 G>C rs1801320, XRCC1 G>A, rs25487 XRCC2 G>A rs3218536 and XRCC3 C>T rs861539 polymorphisms with clinical response of cervical cancer cases (n = 227)." (PMID 35996502, 2022). "SFN treatment and LATS2 overexpression also inhibited cervical cancer survival after irradiation by suppressing Rad51 and MDC1 nucleus recruitment and DNA damage repair." (PMID 35454780, 2022). "Association of genotypes of CYP1A1 T>C rs4646903, CYP1A1 A>G rs1048943, CYP2E1 T>A rs6413432, RAD51 G>C rs1801320, XRCC1 G>A, rs25487 XRCC2 G>A rs3218536 and XRCC3 C>T rs861539 polymorphisms with vital status and recurrence of cervical cancer cases (n = 227)." (PMID 35996502, 2022). "Association of genotypes of CYP1A1 T>C rs4646903, CYP1A1 A>G rs1048943, CYP2E1 T>A rs6413432, RAD51 G>C rs1801320, XRCC1 G>A rs25487, XRCC2 G>A rs3218536 and XRCC3 C>T rs861539 polymorphisms and survival after treatment (CRT) for cervical cancer." (PMID 35996502, 2022). "A combination of Res and RAD51-siRNA induces apoptosis in HeLa cells and prevents cervical cancer progression." (PMID 34769099, 2021). "In conclusion, this study indicates an association of RAD51 rs1801320 and XRCC2 rs3218536 polymorphisms with cervical cancer development in the Bangladeshi population." (PMID 34319032, 2021). "γ-H2AX and Rad51 foci formation, neutral comet assay and clonogenic cell survival assay were applied to determine the radiosensitivity of cervical cancer cells." (PMID 32907622, 2020). "We found that CSC, derived from cervical cancer cell lines, overexpress RAD51 and are less sensitive to Etoposide (VP16)." (PMID 29681946, 2018). "Here, we performed a ‘proof of concept’ study evaluating the role of prelamin A and RAD51 expression in clinical outcome of cervical cancer patients." (PMID 29212225, 2017). "If clinically validated in prospective studies, our data support a role for utilizing prelamin A and RAD51 as predictive biomarkers for the efficacy of neoadjuvant chemoradiation therapy in patients with cervical cancer." (PMID 29212225, 2017). "We observed a 3.4-fold increase in RAD51 mRNA (qRT-PCR data) and also an increased protein expression of RAD51 in the nuclei of the NCR vs. CR cervical cancers." (PMID 24708616, 2014). "Additionally, SFN treatment and LATS2 overexpression prevented MDC1 and Rad51 from accumulating in the nucleus in cervical cancer cells after being exposed to ionized radiation." (PMID 35454780, 2022).
cervical carcinoma (continued). "Our results indicated that SFN could enhance the expression of LATS2 and exert irradiation sensitization in cervical cancer cells by suppressing DNA double-strand break repair, specifically by inhibiting Rad51 and MDC1 nuclear accumulation." (PMID 35454780, 2022). "Previous studies recognized that the overexpression of the RAD51 gene (rs1801320) could trigger the development of various cancers like breast and cervical cancer in humans." (PMID 34319032, 2021). "MiR-4429 promotes cervical cancer cell radio-sensitivity through RAD51." (PMID 32469064, 2020). "However, our work is, to our knowledge, the first involving depletion of RAD51 in CSC from cervical cancer using RES." (PMID 29681946, 2018). "PPARγ influences RAD51 and exposing cells to T0070907 attenuate RAD51 levels and ionizing radiation-induced foci causing centrosome amplification and multipolar mitotic spindle formation in cervical cancer cells but not in wildtype cells." (PMID 31435521, 2018). "In conclusion, our findings, that should be validated in a larger prospective trial, provide a framework for sustaining molecular-based patient-tailored treatments, employing RAD51 inhibitors as single agents or in combination with other therapies for cervical cancer." (PMID 29212225, 2017). "Here, we hypothesized that both RAD51 rs1801320 and XRCC2 rs3218536 are associated with risk of cervical cancer development and performed this case-control study of in the population of Bangladesh to identify the association with the development of cervical cancer." (PMID 34319032, 2021). "Besides, a protective effect on clinical outcome of cervical cancer patients of the RAD51 172TT genotype, has been also reported as a possible consequence of a lower cellular capacity for DSB repair and, in turn, a greater sensitivity to chemotherapeutic agents." (PMID 29212225, 2017). "RAD51, one of the key molecules of DNA repair, is another gene we found to be significantly overexpressed in the NCR cervical cancers." (PMID 24708616, 2014). "An experiment has shown that RAD51 has oncogenic role and enhances CSC features in cervical cancer." (PMID 34769099, 2021). "Alterations in common DNA repair genes (RAD51 and XRCC2) may lead to cervical cancer (CC) development." (PMID 34319032, 2021). "Interestingly, we observed that FEN1, PCNA, RAD51 and RPA1 protein levels were upregulated in cervical cancer derived cell lines as well as in keratinocytes transduced with HPV16 oncogenes when compared to normal PHK." (PMID 30674977, 2019). "Immunohistological staining confirmed increased expression of BRCA1, BRIP1, FANCD2 and RAD51 in non-responsive compared with responsive advanced squamous cervical cancer, both in the initial set of 21 cervical cancer samples and the second set of 24 samples." (PMID 24708616, 2014). "The overexpression of BRCA1, BRCA2, RAD51, BRIP1 (BACH1), FANCD2, BLM and RFC in non-responding versus responding cervical cancer samples suggests that DNA repair mechanism activation occurs through cell cycle arrest and homologous recombination." (PMID 24708616, 2014).